ENSG00000201666
Synonyms: LOC124900494
Gene: Small nucleolar RNA gene on chromosome X (28,924,069 to 28,924,138, forward strand). Ensembl gene ENSG00000201666.
Gene Ontology:
Biological process: RNA processing
Cellular component: nucleolus
Homologues: Orthologues: mouse Gm26224 (76% identical), rat LOC120096384 (73% identical), zebrafish snord74 (66% identical). Paralogues in human: SNORD74B (70% identical).